RPL29P2 (ribosomal protein L29 pseudogene 2 )
Synonyms: RPL29_10_1510
Gene: Long non-coding RNA gene on chromosome 17 (7,754,320 to 7,754,976, forward strand). Ensembl gene ENSG00000293140.
Diseases named in the same sentence as RPL29P2 in open-access papers:
RPL29P2 is named in the same sentence as 3 diseases in open-access papers, as found by Europe PMC text mining. Sharing a sentence is not in itself a finding about the gene and the disease. The quoted sentences say what the papers report.
Peritoneal Fibrosis (1 paper, 2024). Disorder characterized by a wide range of structural changes in PERITONEUM, resulting from fibrogenic or inflammatory processes. "In this study, we found that a new lncRNA, RPL29P2, was upregulated in the peritoneal membrane of long-term PD patients, and its expression level was correlated with peritoneal fibrosis severity." (PMID 38774747, 2024). "SRF-lncRNA RPL29P2 pathway also could presumably enhance peritoneal fibrosis by sponging downstream miRNAs and their target genes or target proteins." (PMID 38774747, 2024). "Finally, our results showed a complete pathway by which the transcription factor SRF could enhance HG-induced peritoneal fibrosis during PD; one pathway functions through direct upregulation of lncRNA RPL29P2 expression." (PMID 38774747, 2024). "More interestingly, RPL29P2 is only one of the target lncRNAs that can be directly regulated by the transcription factor SRF, a promoter of peritoneal fibrosis." (PMID 38774747, 2024).
cancer (1 paper, 2024). A tumor composed of atypical neoplastic, often pleomorphic cells that invade other tissues. "Moreover, RPL29P2 was significantly upregulated in HPMCs and HK-2 cells but exhibited lower expression in these cancer cells." (PMID 38774747, 2024).
tumor (1 paper, 2024). "RPL29P2, as determined by PCR, was expressed at lower levels in human liver and gastric cells and in the corresponding tumor cells than that in other tissues." (PMID 38774747, 2024).